NF1 (neurofibromin 1)
Diseases named in the same sentence as NF1 in open-access papers (continued):
Sharing a sentence is not in itself a finding about the gene and the disease.
tumor (continued). "Recurrent tumor presented the following set of mutations: H3F3A (c.344C > G; p.Ala115Gly), PIK3CA (c.2119G > A; p.Glu707Lys), NF1 (c.7026G > T; p.Leu2342=) and DOCK6 (c.1664C > T; p.Pro555Leu)." (PMID 36611369, 2022). "NF1-mutant SCs therefore gradually rewire the PN microenvironment, to evade immune suppression and generate a permissive environment for tumor growth." (PMID 36134665, 2022). "Among 342 patients with NF1 analyzed, 20 developed neoplasms with a mean of 36.5 (range: 11 to 61) years (SD, 13.9)." (PMID 35506373, 2022). "Two of the children in this series with NF1 had a visible tumor in the contralateral optic nerve with increased signal intensity of the nerve and mild contrast uptake." (PMID 35455503, 2022). "Only microdeletion NF1 patients are known to suffer from a higher tumour burden and more severe phenotype." (PMID 34997843, 2022). "Tumor load was retrospectively measured and enhancement semi-quantitatively scored on 298 MRIs of 35 patients (63% NF1 + OPG)." (PMID 34994964, 2022). "The NF1 tumor-suppressor functions as a GAP for RAS promoting GTP hydrolysis and inhibiting MEK/ERK activation." (PMID 35905710, 2022). "The results yielded in this systematic review and meta-analysis showed that trametinib significantly controlled the tumor progression of NF1-related pNF and LGG, with a pooled DCR of 99.8%." (PMID 36015104, 2022). "Clinically, NF1-derived MPNSTs are often diagnosed at an advanced stage, with primary tumours having reached a diameter of 5–10 cm and even having broken through the sheath membrane with detectable distant metastases." (PMID 36497280, 2022). "NRAS (n = 3) and NF1 co-mutations (n = 2) were identified in PRKCA fusion-positive tumors, and one tumor harbored a PRKCA fusion with NF1." (PMID 35326655, 2022). "Deleterious mutations of the NF1 tumor suppressor gene occurred in three MAPK-AB tumors, the MN1-BEND2-negative MN1-rearranged tumor, and an ATAB." (PMID 35440587, 2022). "Accordingly, NF1 expression is negatively correlated with bulk tumor MES scores across the TCGA GBM cohort." (PMID 36123598, 2022). "NF1, a tumor suppressor gene, codes for neurofibromin, a protein that downregulates the MAPK/ERK pathway." (PMID 36143375, 2022). "Among them, the NF1 mutation was indicated by NGS and confirmed using Sanger sequencing in one tumor (case #3) showing weak-moderate expression of Pan-TRK, and this patient was diagnosed with NF1 syndrome based on the clinical characteristics." (PMID 36612101, 2022). "Like other tumour suppressor genes, NF1 covers both CpG islands, methylated nucleotides, and repeat sequences." (PMID 34997843, 2022). "NF1 is caused by mutations in NF1 (17q11.2), which encodes neurofibromin, a large guanosine triphosphate GTPase-activating protein (GAP), which acts as a tumor suppressor by regulating RAS GTPase." (PMID 35885913, 2022). "Analysis of the stromal compartment in primary tumor specimens revealed that the expression of NF1 (HR = 0.748, p = 0.025), CD27 (HR = 0.279, p = 0.035), and CD80 (HR = 0.703, p = 0.02) was associated with a better OS." (PMID 35651606, 2022).
tumor (continued). "Visual impairment depends on tumour location, age at diagnosis, recurrence and hence repeated treatment rates, and NF1 status." (PMID 35159015, 2022). "SDHB IHC carried out in the tumour carrying co-occurrent SDHB germline mutation and somatic NF1 mutation yielded a positive stain, which is atypical for pathogenic SDHB mutations." (PMID 36760809, 2022). "Though both are in cluster 2, in contrast to the RET gene, NF1 is a tumor suppressor that negatively regulates the RAS-MAPK signaling pathway." (PMID 35903274, 2022). "It is possible that in LMS tumors with high accumulation of DNA damage, disruption of cell cycle checkpoint regulation through RB1, CDKN2A/B, MYC, FBXW7, or NF1 is necessary to maintain the viability of the tumor." (PMID 35468996, 2022). "Due to an increased mutation rate, reduced MMR capacity leads to accumulation of somatic sequence changes in tumour suppressor genes such as in the neurofibromatosis type 1 (NF1) gene." (PMID 34997843, 2022). "To evaluate the impact of tumor cell–intrinsic PRC2 inactivation on the TME in vivo, we generated a histologically confirmed Nf1–/– Cdkn2a/b–/– murine MPNST tumor–derived cell line (SKP605) from skin-derived precursors (SKPs) of C57BL/6J mice." (PMID 35852856, 2022). "As for NF1-related LGGs, our study demonstrated good capability in tumor suppression of trametinib, with the DCR reaching 99.2%, and the objective response rate is yielded as 44.2%." (PMID 36015104, 2022). "The gene product of the NF1 gene is Neurofibromin, which acts as a tumor suppressor and is an important factor for skeletal development." (PMID 34413392, 2021). "Seven of the 64 tumour suppressors (ACVR2A, CSMD3, EPS15, MAP2K4, NF1, PBRM1 and RB1) had intronic mis-splicing mutations in multiple tissues." (PMID 33420369, 2021). "Our results indicate that NF1 whole gene deletions lead to higher tumor burden and higher growth rates." (PMID 33951044, 2021). "Are we able to re-educate these cells in the NF1-null microenvironment to achieve the anti-tumour function?" (PMID 35008787, 2021). "In MPNST driven by NF1 loss, Heat Shock Factor 1 (HSF1) was overexpressed and activated, which was required for increased tumor cell viability." (PMID 34502310, 2021). "These genotype–phenotype correlations in NF1 have presented possible pigment-predominant tumor-free phenotypes." (PMID 34566848, 2021). "A recent study showed that tumor models with codeletion of Nf1 and Pten and overexpression of EGFRVIII had the ability to escape immune clearance and a high degree of immunosuppressive microenvironment, and Nf1 loss was the key event." (PMID 34663417, 2021). "Cabozantinib is a multiple tyrosine kinase inhibitor which, in preclinical and translational studies, modulated key kinases in the TME in Nf1-mutant mice and reduced the PN tumor burden in these mice." (PMID 34885143, 2021). "We conclude that NF experts and patient representatives consent to prioritise development of drug trials for MPNST, benign peripheral nerve sheath tumours, cutaneous manifestations and HGG for NF1; tumours for NF2; and pain for SWN." (PMID 33903738, 2021). "30% (6/20) of the patients with genetically confirmed NF1 had minimum one tumor, 10% (2/20) of which were OPG, and this prevalence approaches the 15–20% cited in the scientific literature." (PMID 34325699, 2021). "Current therapies for NF1-derived pain include generic pain medications and removal of the inciting tumor." (PMID 33669386, 2021). "Neurofibromatosis-1 (NF-1) is an autosomal dominant condition characterized by cutaneous pigmentation and tumour formation along nerves in the brain, skin, and other organs." (PMID 34336521, 2021).
tumor (continued). "Neurofibromin 1 gene is located on the long arm of the chromosome 17 (17q11.2) and codes for neurofibromin, a tumor suppressor that functions in the RAS/MAPK and mTOR pathways and controls the cell growth and proliferation." (PMID 34168676, 2021). "Using computational prediction, we identified NF1 p.T700I and NOTCH1 p.V2153M as tumor-associated neoantigens, representing potential therapeutic targets for immunotherapy." (PMID 34503126, 2021). "All our tumor samples will also be examined for somatic mutations since these are also detected in 30% of sporadic HNPGLs, mainly involving VHL, NF1, RET and HIF2α genes, although these are rarely associated with multiple HNPGLs." (PMID 34072806, 2021). "In summary, the LV-miniMg-∆MEF3/NF1 promoter can drive HSV-TK expression in vivo to slow/prevent tumour growth." (PMID 32973362, 2021). "Primary nf1/pten-mutant tumors are invariably melanotic, but after serial transplantation, the tumor cells often become amelanotic." (PMID 34331013, 2021). "We identified SNVs in the exo-DNA that were not present in tumor DNA at onset of disease, in particular mutations of ALK, ATRX, NF1, and TERT genes, probably coming from other tumor sites." (PMID 33915956, 2021). "NF1 is a tumor suppressor located at 17q11.2; it contains 57 constitutive and three alternative exons and spans over ~350 kb." (PMID 34199217, 2021). "This case report discusses an adult male with NF-1 and a tumor of the splenium of the corpus callosum." (PMID 34909339, 2021). "Some studies have demonstrated that patients with NF1-related tumours have a worse OS than those with sporadic tumours." (PMID 34867073, 2021). "In the NF1 subtype (~10%) the tumor-suppressor NF1 is inactivated, which is a negative regulator of RAS." (PMID 33669371, 2021). "The median tumor volume (387 ml) in our patients with NF1 whole gene deletions was similar to previously reported whole-body tumor volumes in patients with NF1 whole gene deletions (321 ml)." (PMID 33951044, 2021). "Dysregulation of EGFR caused by mutation, amplification, and overexpression plays a key role in tumor progression of NF1-MPNST." (PMID 34948100, 2021). "While no amplifications were noted in any ERMS of our cohort, one DICER1-wt tumor harbored a somatic deletion including the NF1 locus." (PMID 33846547, 2021). "The wildtype Nf1 tumor microenvironment demonstrated greater radiosensitivity at the lower radiation dose compared to the heterozygous Nf1 tumor microenvironment, although the most severe reduction in survival was observed in Nf1fl/- mice." (PMID 34131650, 2021). "Taken together, different types of NF1 gene mutations and modifiers play an essential role in PNF tumorigenesis and tumor development." (PMID 34566848, 2021). "Western blot for BAX from 6 independent tumour lysates revealed approximately twofold more BAX protein in LV-miniMg-∆MEF3/NF1-HSV tumours compared to LV-∆miniMg-HSV controls." (PMID 32973362, 2021). "Lately, the discovery of biallelic inactivation of the NF1 gene or a “second hit” that occurs specifically within the α-smooth muscle actin-positive cells of the glomus body has been added to an NF1-related tumor spectrum." (PMID 33530415, 2021). "The second noticeable gene whose mutations hyperactivate RAS/RAF/MEK/ERK signaling in cancer is NF1 that encodes a RAS-GAP and functions as a tumor suppressor." (PMID 35582307, 2021). "Thirty-two patients (53.3%) had tumours that were related to NF1, and 28 (46.7%) had sporadic tumours." (PMID 34867073, 2021). "The identification of two patients with tumor predisposition variants (FANCA, NF1) again confirms that the strategy of a broad testing is needed in patients diagnosed with SRS." (PMID 33482836, 2021).
tumor (continued). "In vivo, tumour size was significantly reduced by miniMg-∆MEF3/NF1-HSV in an ARMS xenograft mouse model treated with GCV." (PMID 32973362, 2021). "In this study, we systematically explored the suitability of fourteen candidate reference genes for normalization of gene expression in different NF1 related cell lines, including non-tumor NF1+/- Schwann cell lines, pNF cell lines and MPNST cell lines." (PMID 33630851, 2021). "Some studies have observed a paradoxical activation of tumor growth with BRAF/MEK inhibitor treatment, especially in KIAA1549-BRAF- and NF-1-mutated pLGG." (PMID 34828788, 2021). "The best characterized of the five microRNA genes within the NF1 gene region is miR-193A which is known to possess tumour suppressor functions." (PMID 34535841, 2021). "Tumour-infiltrating lymphocytes are enriched in MES GBM and are strongly associated with NF1 mutations." (PMID 35008787, 2021). "We assessed the percentage of cells with homozygous and heterozygous deletions and defined “deletion” if the percentage of either the NF1 or p16 deletion signals was greater than 50% of tumor cells." (PMID 34461930, 2021). "Individual loss-of-function mutations in the TAOK1, GDI2, NF1, and APC genes resulted in transformation of immortalized human Schwann cells and tumor formation in a xenograft model." (PMID 33808166, 2021). "The model was adjusted to the stage, tumor location (superficial/deep), the presence of distal and/or nodal metastases, and diagnosis of NF1." (PMID 33810575, 2021). "The second patient with a known NF-1 (patient 6) is different from our other five cases in terms of tumor location, radiological and histological aspect and therapy approach." (PMID 33905054, 2021). "Here, we provide evidence that manipulation of NF1 expression levels in patient-derived BTSCs has a direct consequence on the tumor-intrinsic MGS activation and that such activation can at least in part be mediated by the modulation of FOSL1." (PMID 34399888, 2021). "All genetically engineered models can be also modified by crossing them with mice that have specific genetic defects to assess the contribution of specific genes on the NF1- related tumors in tumor cells or their microenvironments." (PMID 34359780, 2021). "An additional approximately 20% of cases were due to alteration in the upper segment of the ERK signaling pathway, namely NF1 tumor suppressor, in the subgroup G3/NF1, or RAF family members, in the subgroup G4/RAF." (PMID 34572759, 2021). "Loss of NF1 is also seen in most sporadic MPNSTs, suggesting that NF1 is an important tumor suppressor in all types of MPNST." (PMID 34502310, 2021). "Although somatic mutational changes within the BRAF, NRAS, NF-1, and KIT genes are seen to deregulate tumor biology within the melanocytes, acknowledgment of the contributory role of inherited factors is also due." (PMID 34155457, 2021). "The larger size and deeper location of the tumour and more frequent truncal location of NF1-related MPNST have accounted for poor outcomes." (PMID 34867073, 2021). "We investigated the stability of these eleven reference genes in fourteen different NF1 related cell lines, including two non-tumor NF1+/- Schwann cell lines, five benign pNF cell lines and seven malignant MPNST cell lines." (PMID 33630851, 2021). "ARID2, NF1, and PIK3CG mutations are associated with poor tumor differentiation and the epithelial–mesenchymal transition." (PMID 34158601, 2021). "Together, these findings point to genetic background effects on survival and tumor progression after spinal irradiation and directly inform clinical considerations in the treatment of patients with NF1." (PMID 34131650, 2021). "In this cohort, the presence of an HR-DDR pathway gene mutation was associated with a significantly higher proportion of thinner primary tumours, head and neck primary tumours, higher tumour mutational burden (TMB) and concurrent NF1 mutation." (PMID 34572747, 2021).
tumor (continued). "The aim of this study was to identify the optimal reference genes for the relative quantitative analysis of RT-qPCR in fourteen NF1 related cell lines, including non-tumor, benign and malignant Schwann cell lines." (PMID 33630851, 2021). "Consequently, we performed whole exome sequencing (WES) of 2XSB cells and their parent tumor and asked whether they contained pathogenic mutations in any of the genes previously implicated in the pathogenesis of NF1-associated MPNSTs or included in the Bushman Laboratory Cancer Gene List." (PMID 33707600, 2021). "NF1 acts as a tumor suppressor through inactivating Ras activity; therefore, when NF1 is mutated, Ras-related signal pathways, e.g., MEK–ERK, and PI3K-AKT pathways, are hyperactivated, which results in poor clinical outcomes for cancer patients." (PMID 34552618, 2021). "This multifaceted disorder is caused by autosomal dominantly inherited or de novo pathogenic variants in NF1 (MIM *613113), a large tumor suppressor gene located at 17q11.2 and spanning ~350 kb of genomic DNA sequence." (PMID 33919865, 2021). "The activity of AKT and mTOR is crucial for the malignant behaviour of NF1-associated neoplasms such as MPNST or optic pathway gliomas, as well as for other tumour entities such as hepatocellular carcinoma and cholangiocarcinoma." (PMID 32102484, 2020). "For example, trametinib alone resulted in moderate tumor inhibition in NF1-MET tumors, yet combined trametinib + doxorubicin significantly improved the response in comparison to single-agent treatment with trametinb or doxorubicin." (PMID 32245042, 2020). "The significant prognostic factors for survival were NF1 status, tumor size, depth, location, malignant grade, margin status, chemotherapy, and radiotherapy." (PMID 32998743, 2020). "Alterations in PRC2 core components were detected in 13/16 (81%) tumours in the setting of NF‐1 and in 12/21 (57%) sporadic tumours." (PMID 32666581, 2020). "Loss of NF1, therefore, leads to constitutive activation of RAS signaling, likely accounting for the pro-tumor phenotype observed in patients with NF1." (PMID 32599735, 2020). "This reduction in copy ratio around the NF1 locus in the tumor tissue, indicated by the black arrow, was preserved across the cell line and xenograft models derived from the same patient." (PMID 32561749, 2020). "Our findings indicate that NF1, a tumor-suppressor gene that negatively regulates the RAS signaling pathway was more often mutated in the high-risk subtype (14.1% versus 6.0% in the low-risk subtype, Fisher test p = 0.01)." (PMID 32235589, 2020). "At 21 days, significant tumor inhibition was observed in NF1-MET tumors and in the surviving cells, the kinome adaptations observed with single MET inhibition were intensified." (PMID 32245042, 2020). "EGFR exon 19 deletion (ex 19 del) mutation in Case. was detected only in tumor sample and EGFR ex 19 del in Case. and NF1 R1870W in Case. mutations were detected only in peeling archival samples, respectively." (PMID 32351019, 2020). "Individuals with constitutional mismatch repair (MMR) deficiency, a rare tumor predisposing syndrome caused by biallelic mutations in one of MMR genes, display features reminiscent of NF1." (PMID 32575496, 2020).